PLK1 (polo like kinase 1)
Diseases named in the same sentence as PLK1 in open-access papers (continued):
Sharing a sentence is not in itself a finding about the gene and the disease.
tumor (continued). "In clinical tumor tissues, protein expression of SPIB, PLK1, and CD24 was up-regulated, while protein expression of NTRK3 and EDA2R was down-regulated." (PMID 39596658, 2024). "The proteins PLK1, SPIB, and CD24 show darker staining in tumor tissues, while NTRK3 and EDA2R exhibit lighter staining in tumor tissues." (PMID 39596658, 2024). "In iCCA, PLK1 and MISP promote aggressiveness by increasing lymphatic invasion, tumor growth, and motility through the repression of E-cadherin adherens junctions." (PMID 38057358, 2024). "T7E1 digestion assay results demonstrated that ANC@RNP achieved more potent activity at EGFR and PLK1 gene sites versus non‐targeted NC@RNP after 48 h incubation in U87MG cells, signifying the importance of ApoE‐ligand in tumor targeting." (PMID 38943253, 2024). "In sum, PLK1 expression is increased in HCC, particularly in the context of tumour metastasis and vascular invasion, suggesting a role for PLK1 in HCC cell motility." (PMID 37648284, 2023). "According to the TISIDB study, PLK1 expression is positively correlated with the infiltration of activated CD8+ T cells, which have a substantial anti‐tumor role." (PMID 36951624, 2023). "Our in vitro and in vivo findings suggest that the phosphorylation of survivin by PLK1 and AURKB promotes tumor cell proliferation and cell cycle progression in AA TNBC cells but not in EA TNBC cells." (PMID 36627281, 2023). "Concurrent targeting of KRAS and ST8SIA6-AS1/PLK1 signaling suppressed both ERK-dependent and -independent c-Myc expression, synergistically led to cell death and tumor regression and overcame KRASG12Ci resistance." (PMID 38104151, 2023). "Our findings have important clinical ramifications as they provide a rationale for targeting PLK1 to treat HCC and support early treatment to prevent tumour progression, particularly in patients with virus-induced HCC." (PMID 37648284, 2023). "Notably, this intervention prompted the polarization of M1 tumor-associated macrophages and the maturation of dendritic cells within the tumor microenvironment (TME).Furthermore, the targeted application of siRNAs against PLK1 or PD-L1 elicited potent gene silencing in cancer cells." (PMID 38239346, 2023). "Exosome-loaded siRNA therapeutics have been effective in downregulating BCL-2, PLK1, KRAS, and survivin anti-apoptotic proteins that induce tumor cell mitosis and cell growth factor." (PMID 36678782, 2023). "Mechanistically, silencing AFAP1-AS1 inhibited PLK1 phosphorylation and thereby promoted mitotic catastrophe in TNBC primary cells and tumor metastasis in vitro." (PMID 37305386, 2023). "Catalytically active PLK1, a kinase of FoxM1 in mitosis, drives the EMT and promotes tumor survival through activation of TGF-β signaling and PD-L1 expression." (PMID 37968723, 2023). "As expected, tumor tissues from these animals showed decreased levels of ST8SIA6-AS1 expression and suppressed Aurora A/PLK1 signaling activation." (PMID 38104151, 2023). "PLK1 inducible overexpression leads to WGD by cytokinesis abscission impairment, promoting a strong brake in cell transformation and tumor progression." (PMID 37342233, 2023). "AFAP1-AS1 promoted proliferation, migration and invasion, inhibited mitotic catastrophe in TNBC primary cells, and accelerated tumor growth in TNBC PDX and lung metastasis by activating PLK1." (PMID 37305386, 2023). "To better understand the molecular signatures after the combined inhibition of UBE2C and PLK1 in Lv-NCI-H460 and Lv-MCF7 tumor cells, we performed an RNA-seq analysis and analyzed the DEGs." (PMID 37958642, 2023). "Compared to normal lung tissues, both PLK1 and DIO2 levels were elevated in tumor samples and at higher stages of LUAD." (PMID 37988371, 2023). "Compared with normal tissues, the expression level of PLK1 was slightly higher, while that of UBE2C was obviously higher than tumor samples." (PMID 37958642, 2023).
tumor (continued). "The overexpression of FANCI, CHK1, and PLK1, as well as the overactivation of the DDR pathway, cooperate to promote the cell cycle process and the division of the tumor cells." (PMID 37324186, 2023). "Xenograft models of aRMS treated with the PLK1 inhibitor, BI 2536, showed decreased expression of PAX3-FOXO1 target genes and eventually led to a complete tumor regression." (PMID 37174744, 2023). "Our data suggest that survivin phosphorylation at S20 and T117 by PLK1 and AURKB is essential for tumor progression in AA patients with TNBC and contributes to racial disparities in TNBC." (PMID 36627281, 2023). "PLK1 regulated the degree of immune cell (e.g., CD8+ T cells, Tregs, etc.)infiltration and immunomodulator expressions, thus participating in the tumor‐specific immune response." (PMID 36951624, 2023). "In a mouse xenograft tumor model, FRL‐triggered PLK‐1 oncogene editing was successfully achieved using FAST system." (PMID 36925702, 2023). "By integrating siRNAs targeting polo-like kinase 1 (PLK1) and vascular endothelial growth factor receptor-2 (VEGF2), the Ang-3I-NM@siRNA effectively suppressed the GBM tumor growth." (PMID 36752939, 2023). "PLK1 inhibition with Volasertib (i.e., BI6727) results in tumor growth suppression in NB xenografts." (PMID 37760568, 2023). "The result indicated the suppression of PLK1 protein, with the inhibition of the TNBC tumor revealing αHB-EGF LNP siRNA as a prospective target for TNBC tumors expressing HB-EGF." (PMID 36678782, 2023). "Investigations demonstrate that a combination of PLK1 (BI2536) and Bcl-2 (ABT199) inhibitors synergized and induced apoptosis in FBXW7 low, and c-MYC overexpressing, tumor cells." (PMID 35346215, 2022). "The expression patterns of PLK1 and CDKN2A were considerably up-modulated in most tumour types, while KLF9 was the opposite." (PMID 36186436, 2022). "Polo-like kinase 1 (PLK1), which is highly expressed in tumor cells, is a key serine/threonine kinase involved in many important cell cycle functions such as mitotic entry, centrosome maturation, cell cycle progression, and cytoplasmic division." (PMID 36091753, 2022). "In routine, it promoted the expression of polo-like kinase-1 (PLK1) by competitively binding to miR-1224-3p, and circ-ZNF609 also promoted tumor growth in vivo." (PMID 35938040, 2022). "Among these genes, PLK1, CDC25C, ESCO2, AXIN2, TREX2, ALKBH2, and MC1R were upregulated in tumor tissues, whereas IGF1 and ESR1 presented downregulation." (PMID 35484177, 2022). "Based on the DPRP surface modification, we developed a pH-responsive liposomal system for co-delivering polo-like kinase-1 (PLK-1) specific siRNA and anticancer agent docetaxel (DTX), D-Lsi/DTX, to synergistically exhibit anti-tumor effect." (PMID 35366888, 2022). "In short, PLK1 expression contributes to immunosuppressive TME, inhibiting immune cell infiltration and anti-tumor immunity." (PMID 35871223, 2022). "There was a 3.3 ± 0.3 and 3.4 ± 0.6-fold increase in PLK1 expression in A549 and NCI-H460 cell lines, respectively, compared to the lung non-tumor cell line." (PMID 35745782, 2022). "Of the SAC genes overexpressed in the OB tumor cells, TKK, PLK1, CDK1, BUB1 and BUB1B have been shown to play a role in radiosensitivity." (PMID 36482431, 2022). "The PLK1 activity controls a polarity checkpoint and compensates for BRAF/MAPK inhibition in CD133(+) tumor cells, suggesting the need for concurrent PLK1 inhibition to improve antitumor activity against a therapy-resistant cell compartment." (PMID 36686797, 2022). "In an early research, an ApDCs was constructed using a PSMA-targeting aptamer and a small interfering RNA (siRNA), which can silence polo-like kinase 1 (PLK1) and B-cell lymphoma 2 (BLC2) overexpressed in most human tumor cells." (PMID 36051580, 2022).
tumor (continued). "Among them, many regulatory enzymes have a remarkable role, including polo-like kinase-1 (PLK-1), which is identified as a critical player in G2/M transition and mitotic progression in both tumor and normal cells." (PMID 36358278, 2022). "STAT3, an important member of the JAK/STAT signaling pathway, is negatively regulated or activated by PLK1, leading to the up-regulation of the downstream gene MMP2, thereby enhancing the aggressiveness of tumor cells." (PMID 34858165, 2021). "Our results suggested that PLK1 blockade indirectly elicited the activation of DCs to prime T cells, possibly via ICD-related increase in phagocytosis of specific tumor antigens and expression of costimulatory molecules on DCs." (PMID 34522178, 2021). "Further studies revealed that PLK1 inhibitors served as an ICD inducer to expose the markers of ICD, which enhanced the DC phagocytosis and activated DCs, and helped protect mice from tumor challenge." (PMID 34522178, 2021). "Regarding the molecular mechanism, we found that ALDOA inhibited the DDR and improved activation of the cell cycle checkpoint PLK1 by suppressing ATM, which promotes tumour cell progression." (PMID 34565365, 2021). "The tumor-suppressive role of PLK2, and its relationship with oncogene PLK1, provide a mechanistic rationalization to use PLK1 inhibitors in combination with chemotherapy to treat PLK2-low/deleted tumors." (PMID 35156101, 2021). "Nevertheless, although not reaching significance, there was a trend of reduced expression of PLK1, KIF11, PTTG1 and TTK (the latter otherwise induced by DEXA in U25MG cells in DEXA treated tumours." (PMID 33478100, 2021). "The cationic TAT peptide can guide pCas9/sgPLK-1 (Polo-like kinase 1) to enter the nucleus and destroy the PLK-1 gene, thus inhibiting tumor growth." (PMID 34054927, 2021). "Cell lines and primary normal or tumor cells with an active VHL (A, C2, 15S, TF) have undetectable or low levels of Plk1 as compared to VHL-i cell lines and primary cells (R4, R10, 786, 498, MM, CC)." (PMID 33547392, 2021). "Here, we show in the EwS model how uncoupling of mitosis and cytokinesis via targeting protein regulator of cytokinesis 1 (PRC1) or its activating polo-like kinase 1 (PLK1) can be employed to induce fatal genomic instability and tumor regression." (PMID 34531368, 2021). "Similar to cluster 3, cluster 8 exhibited high expression of Aurkb, Plk1, and other genes that suggest that these NKX2-1-positive tumor cells are in G2/M phase." (PMID 33821796, 2021). "PLK1 expression was conspicuously higher in LUAD tumors than in normal samples, and was positively correlated with tumor stage." (PMID 34522178, 2021). "TKM-080301 is composed of a siRNA encapsulated in LNPs that can target polo-like kinase 1 (PLK1), which regulates critical aspects of tumor progression." (PMID 33918072, 2021). "In fact, 3 of top 5 kinase genes include CDK1, PLK1, and AURKB were significantly highly expressed in tumor tissues and significantly related to the overall survival of LUAD." (PMID 33178836, 2020). "HMMR acts as an essential component during the polo-like kinase 1 (PLK1)-dependent mitotic spindle positioning pathway, which is required for neural development, neonatal survival, and tumor formation." (PMID 33061798, 2020). "PLK1 and AURKC downregulation was also detected in BRDT-KO CaOV3 tumor tissues and in pOS-1 xenografts with BRDT shRNA injection." (PMID 33257688, 2020). "In fact, 3 of the top 5 kinase genes include CDK1, PLK1, and AURKB, were significantly highly expressed in tumor tissues and significantly related to the overall survival of LUAD." (PMID 33123291, 2020).
tumor (continued). "In fact, PLK1, CDK1, and AURKB were significantly upregulated in tumor tissues, by contrast, ATM was markedly downregulated expressed in tumor tissues, except CDK2." (PMID 33292231, 2020). "Taken together, these results support cMet as a driver of Plk1 inhibitor resistance in epithelial NSCLC in vivo, and the findings suggest that co‐inhibition of Plk1 and cMet increases apoptosis, leading to tumor regression in NSCLC." (PMID 31040125, 2019). "In the case, PLK1, BCL2, and STAT3, three important proteins with high relevance in tumor growth, were selected." (PMID 31888119, 2019). "PLK1 is overexpressed in HCC samples relative to normal controls, and its knockdown can induce apoptosis of tumor cells via the endonuclease-G pathway." (PMID 30705088, 2019). "The expression of PLK1 and CHEK1 was significantly higher in tumor tissues than in normal tissues, whereas WEE1 expression was significantly lower in tumor tissues than that in normal tissues." (PMID 31387297, 2019). "Plk1 regulators Cdc14B and APC/Ccdh1 have been found to be downregulated in several tumor types including prostate and brain cancer." (PMID 29402316, 2018). "Inhibitors of PLK1, such as BI 6727 or BI2356, preferentially induce potent apoptosis of Myc-overexpressing tumor cells and synergistically potentiate the therapeutic efficacies of BCL-2 antagonists." (PMID 29527331, 2018). "There are a further eight tumor-suppressor genes (DLEU2, CDKN2C, SPRY4, UBE2QL1, LIN9, TFPI2, LRIG3, DUSP1) and six genes serve as both oncogenes and tumor-suppressor genes (FOXO1, CAV1, KLF6, CDK6, PLK1, CTGF)." (PMID 30563222, 2018). "In the 5637 xenograft model, the reduction of the tumour weights corresponded to the increase in Wee1 expression, CDC2 (Thr14/Tyr15) phosphorylation and the reduction in PLK1 expression." (PMID 27878946, 2017). "Paired tissue analysis in 3 evaluable patients also identified PLK1, BUB1, and PBK as the top genes overexpressed in tumor relative to adjacent normal samples." (PMID 28423512, 2017). "Gene expression analysis showed that PLK1 was overexpressed in ATRT patient samples and tumor cell lines." (PMID 29228610, 2017). "Doxycycline (Dox) treatment administered in the drinking water, which suppressed Plk1 expression, dramatically abolished WT G6PD-promoted tumor growth." (PMID 29138396, 2017). "Here, we will discuss the recent advances in the understanding of PLK1 as an oncogene, with a focus on its role in epithelial-mesenchymal transition (EMT) and tumor invasion." (PMID 28953239, 2017). "WEE1 and PLK1 are involved in the G2/M phase of cell cycle regulation, and TAK1 is an upstream activator of the tumor-promoting NF-kB signaling." (PMID 27558154, 2016). "Here, the authors perform a synthetic lethal screen in mice and show that inhibiting Plk1 and ROCK results in the inhibition of tumour growth by increasing expression of the tumour suppressor p21." (PMID 27193833, 2016). "In this context, systematic administration of Plk1 inhibitors could reduce dramatically ASCs viability and impair their functionality by inducing apoptosis and altering their biological features like anti-inflammation, which are pivotal for the fate of tumor cells." (PMID 27713178, 2016). "We also highlighted certain potential mechanisms responsible for the tumor suppressor effect of SLAMF3 by inhibiting the MAPK/ ERK1/2 phosphorylation and blocking the cell cycle at G2/M in an RB/PLK-1 dependent-manner." (PMID 27081035, 2016). "Comparison of PLK1 expression in HCC tumors and their corresponding tumor free tissue showed that it is overexpressed in the tumoral tissue." (PMID 26799423, 2016). "Our present work provides the framework for such a context, i.e. PLK1 overexpression, in which PP2A inhibition can be effective in killing the tumor cells." (PMID 27557495, 2016). "Plk1 is overexpressed at the mRNA and protein level in RCC patient tissues and this overexpression is correlated with the tumor grade and metastases." (PMID 26579493, 2015).
tumor (continued). "The 12 variables of interest included TP PLK1 weighted score, age, gender, TNM stage, histological grade, vascular invasion, perineural invasion, presence of tumour-infiltrating lymphocytes, adjuvant chemotherapy and neoadjuvant treatment." (PMID 26047016, 2015). "PLK1 inhibition by a combination of rigosertib and ABL TKIs offers a novel targeted anti-tumor therapy for patients with Ph-positive leukemia." (PMID 26008977, 2015). "After evaluating by different clinicopathological variables, age, tumor size, tumor nodule, clinical stage, HBV positive, HCV positive, liver function, and with or without tumor thrombi in portal vein showed less correlation with PLK1 expression." (PMID 25019081, 2014). "SNALP-formulated siRNA targeting the essential cell-cycle proteins polo-like kinase 1 (PLK1) and kinesin spindle protein (KSP) showed potent antitumor efficacy in both hepatic and subcutaneous tumor models." (PMID 23844368, 2013). "The present study has shown that PLK1 interference suppressed ARO cell invasion and decreased CD44v6 activity, which supports the involvement of CD44v6 in tumor invasion and metastasis." (PMID 23226764, 2012). "Some of the genes identified here are already used to predict tumor recurrence and the response to treatment, while AURKA and PLK1 are frequently included in "poor prognosis" signatures." (PMID 21352579, 2011). "As a positive control for siRNA mediated tumor cell death, SW620 cells were electroporated with a PLK1 siRNA (1 μM)." (PMID 20067634, 2010). "The Polo-Like Kinase 1 (PLK1) acts as a central regulator of mitosis and is over-expressed in a wide range of human tumours where high levels of expression correlate with a poor prognosis." (PMID 20711360, 2010). "In addition, the levels of PLK1 in a subset of tumor types may provide prognostic value." (PMID 20126259, 2010). "Overexpression of Plk1 in NIH3T3 fibroblasts transformed the cells into oncogenic foci in soft agar and more importantly lead to tumor formation when injected into nude mice." (PMID 19161615, 2009). "As mentioned for PLK1, nearly all PLK3-negative tumours expressed inhomogeneously small, albeit detectable amounts of cytoplasmatic PLK3 protein." (PMID 14970859, 2004). "PLK1, another key substrate of AURKA, is typically overexpressed in tumor cells." (PMID 41515655, 2026). "Key mitotic regulators, including kinases such as PLK1, AURKA, AURKB, and MPS1 and kinesins such as CENPE and Eg5, are frequently overexpressed in NSCLC and SCLC, contributing to chromosomal instability, aneuploidy, and highly proliferative tumor phenotypes." (PMID 42076055, 2026). "Notably, several members of the panel, PLK1, UHRF1, and HJURP, have known roles in mitotic regulation and chromatin remodelling, both of which intersect with ferroptotic sensitivity and tumour aggressiveness." (PMID 41007424, 2025). "To further assess whether active PLK1 was associated with MYC or HSF1 in primary samples of patient with HGSOC, we performed IHC for active PLK1 (pT210), HSF1, and MYC using 58 tumor samples of patients with HGSOC." (PMID 39831777, 2025). "In vivo administration of the PROTAC resulted in a marked (75%) reduction in PLK1 levels and tumor volume in a HeLa xenograft, with no apparent systemic toxicity." (PMID 41362117, 2025). "Notably, recent studies have revealed that activated PLK1 in tumors can directly phosphorylate AKT, thereby potentiating tumor malignancy." (PMID 40534847, 2025). "Notably, when PCA was repeated using only the six prognostic genes (AQP4, CDCA3, HJURP, KIF20A, PLK1, UHRF1), tumour and normal samples remained partially separable." (PMID 41007424, 2025).